CPB2-AS1 (CPB2 antisense RNA 1)
Gene: Long non-coding RNA gene on chromosome 13 (46,052,497 to 46,161,379, forward strand). Ensembl gene ENSG00000235903.
Gene Ontology:
Biological process: miRNA-mediated post-transcriptional gene silencing